ENSG00000267385 (novel protein)
Gene: Protein-coding gene on chromosome 19 (4,528,427 to 4,540,067, reverse strand). Ensembl gene ENSG00000267385.
Genetic constraint (gnomAD): Missense variants: 130 observed, 98.74 expected, observed/expected ratio (o/e) 1.32, 90% interval 1.14 to 1.52. Synonymous variants: 56 observed, 41.46 expected, observed/expected ratio (o/e) 1.35, 90% interval 1.09 to 1.68.